DZIP3 (DAZ interacting zinc finger protein 3)
Description:
E3 Ubiquitin ligase proteins mediate ubiquitination and subsequent proteasomal degradation of target proteins. E3 ubiquitin ligases accept ubiquitin from an E2 ubiquitin-conjugating enzyme in the form of a thioester and then directly transfers the ubiquitin to targeted substrates. Able to specifically bind RNA.
Synonyms: hRUL138; PPP1R66; UURF2
Tractability: PROTAC: ubiquitination databases record sites on it; its protein half-life has been measured.
Gene: Protein-coding gene on chromosome 3 (108,589,480 to 108,694,846, forward strand). Ensembl gene ENSG00000198919.
Subcellular location: Cytoplasm
Subcellular location (Human Protein Atlas): Vesicles
Pathways (Reactome):
Immune System: Antigen processing: Ubiquitination & Proteasome degradation
Gene Ontology:
Molecular function: phosphatase binding; polyubiquitin modification-dependent protein binding; protein binding; RNA binding; ubiquitin-protein transferase activity; ubiquitin protein ligase activity
Biological process: protein polyubiquitination; protein ubiquitination
Cellular component: cytoplasm
Genetic constraint (gnomAD): Loss-of-function variants: 76 observed, 117.81 expected, observed/expected ratio (o/e) 0.65, 90% interval 0.54 to 0.78. The upper end of that interval is the gene's LOEUF score, 0.78, which puts it in group 3 of 6, group 1 being the genes least tolerant of losing a copy. Missense variants: 1,072 observed, 1,198.4 expected, observed/expected ratio (o/e) 0.89, 90% interval 0.85 to 0.94. Synonymous variants: 363 observed, 395.6 expected, observed/expected ratio (o/e) 0.92, 90% interval 0.84 to 1.
Homologues: Orthologues: chimpanzee DZIP3 (99% identical), macaque DZIP3 (95% identical), dog DZIP3 (91% identical), rabbit DZIP3 (91% identical), pig DZIP3 (89% identical), mouse Dzip3 (83% identical), guinea pig DZIP3 (82% identical), rat Dzip3 (82% identical), Drosophila melanogaster sip3 (9% identical), Caenorhabditis elegans sel-11 (8% identical), zebrafish zmp:0000000662 (7% identical), tropical clawed frog rnf145l (6% identical), and 1 more. Paralogues in human: SYVN1 (11% identical), RNF145 (7% identical), AMFR (5% identical), RNF139 (5% identical).
Diseases named in the same sentence as DZIP3 in open-access papers:
DZIP3 is named in the same sentence as 7 diseases in open-access papers, as found by Europe PMC text mining. Sharing a sentence is not in itself a finding about the gene and the disease. The quoted sentences say what the papers report.
breast carcinoma (2 papers, 2016 to 2022). "DZIP3 is known to bind to the coactivator-associated arginine methyltransferase 1 (CARM1) protein, which promotes oestrogen receptor α-mediated transcription in breast cancer." (PMID 35993275, 2022). "Although GAIT activity has not been demonstrated in other cell types, including breast cancer cells, several genes predicted to be regulated by GAIT, such as RORA, NRIP1, and DZIP3 have been shown to mediate ERα-dependent proliferation of breast cancer cells." (PMID 27612429, 2016).
colon cancer (1 paper, 2020). "Interestingly, however, no article has reported the association of DZIP3 with colon cancer or even cancer." (PMID 33330022, 2020). "By collecting a cohort of 100 colon cancer patients and 50 healthy individuals, we validated that the 1st exon DNA methylation of DZIP3 could predict the onset of early stage (AUC = 0.833, OR = 8.82) and all pTNM stages of colorectal cancer (AUC = 0.782, OR = 5.70)." (PMID 33330022, 2020).
glioma (1 paper, 2020). A benign or malignant brain and spinal cord tumor that arises from glial cells (astrocytes, oligodendrocytes, ependymal cells). "Biomedical analyses revealed that DZIP3 is significantly related to angiogenesis, which is the formation of new blood vessels and a prominent hallmark of glioma." (PMID 33229627, 2020). "In the present study, we recruited 590 glioma patients from CGGA RNA-seq (training set), and GSE 16011 array (validation set) sets to compare the mRNA expression level of DZIP3 from different clinical and molecular glioma subtypes." (PMID 33229627, 2020). "Lower-grade glioma patients with lower DZIP3 expression have similar survival time with GBM, while the survival time of the other patients is similar to that of the IDH1 mutation group." (PMID 33229627, 2020). "Gene enrichment analysis and immunohistochemistry indicated that DZIP3 affected the biological behavior of glioma through the angiogenesis pathway." (PMID 33229627, 2020). "DZIP3 was an independent predictive factor of good prognosis in all grade and lower grade gliomas (p < 0.0001)." (PMID 33229627, 2020). "Gene enrichment analysis and immunohistochemistry (IHC) confirmed that DZIP3 could block glioma progression by affecting angiogenesis." (PMID 33229627, 2020). "Therefore, using DZIP3 target medicine for the treatment of glioma warrants for further investigation." (PMID 33229627, 2020). "A total of 261 genes were found to be significantly negatively related with the expression of DZIP3 as assessed by Pearson’s correlation analysis (Pearson |R| > 0.4) in the CGGA RNA-seq and GSE 16011 array cohorts to explore the biological roles of DZIP3 in gliomas." (PMID 33229627, 2020). "In the current study, we utilized two independent cohorts to deduce the role of DZIP3 in glioma." (PMID 33229627, 2020). "In lower-grade glioma, DZIP3 expression could predict the survival time in IDH1 mutant and IDH1 wild-type subgroups." (PMID 33229627, 2020). "Thus, assessing DZIP3 might aid in precise diagnosis of glioma, especially lower grade glioma, and provide a new target for glioma diagnosis and treatment." (PMID 33229627, 2020). "Also, these results could be validated in GSE 16011 array cohort, indicating that the introduction of DZIP3 could provide the basis for accurate diagnosis and treatment of glioma, especially lower-grade glioma." (PMID 33229627, 2020). "DAZ-interacting zinc finger 3 (DZIP3), acts as an RNA-binding RING-type ubiquitin ligase; however, its function in glioma is yet unclear." (PMID 33229627, 2020). "DZIP3, also known as DAZ-interacting zinc finger protein 3, is an RNA-binding RING-type ubiquitin ligase and involved in various biological functions in glioma." (PMID 33229627, 2020). "IHC was used to evaluate the correlation between DZIP3 expression and CD31 (a novel angiogenesis marker); DZIP3 mainly expressed on vascular endothelial cells and was negatively associated with CD31 at the protein level indicating that DZIP3 could affect the angiogenesis process of glioma." (PMID 33229627, 2020). "Then, Cox regression analysis verified the independence of the clinical prognostic significance of DZIP3 in glioma after adjusting age at diagnosis and WHO grade and IDH1 status in both all grade and lower grade glioma in CGGA RNA-seq cohort." (PMID 33229627, 2020). "According to the results mentioned earlier, higher DZIP3 expression indicated a prolonged survival time in all grade and lower grade glioma, but not in GBM." (PMID 33229627, 2020). "However, to the best of our knowledge, no study has explored the correlation between DZIP3 and gliomas." (PMID 33229627, 2020). "Moreover, based on DZIP3 expression, IDH1 wild-type lower-grade gliomas could be divided into two groups with different survival time." (PMID 33229627, 2020). "Moreover, based on DZIP3 expression, we could reclassify the IDH1 wild-type lower-grade glioma." (PMID 33229627, 2020).
melanoma (1 paper, 2022). A malignant, usually aggressive tumor composed of atypical, neoplastic melanocytes. "In addition, this study revealed an increase in Adenosine-to-Inosine editing in Alu regions and in non-repetitive regions, including the hyperediting of the MOK and DZIP3 genes in relapsed tumour samples during targeted therapy and of the ZBTB11 gene in NRAS mutated melanoma cells." (PMID 35993275, 2022).
tumor (4 papers, 2020 to 2024). "Ischemia very interestingly appears to slowly breach through this coping mechanism by causing a decrease in tumor survival-critical proteins such as NUDT1, ELOVL5, HPGDS or DZIP3." (PMID 39327466, 2024).
cancer (3 papers, 2020 to 2022). A tumor composed of atypical neoplastic, often pleomorphic cells that invade other tissues. "Considering the association between DZIP3 and cancer, we designed a low-cost nucleic acid mass spectrometry kit, which was validated by recruiting patients with early CRC." (PMID 33330022, 2020). "The next step is to focus on whether DZIP3 plays an important role in the development of other types of cancer and on ubiquitinated pathway-modified proteins." (PMID 33330022, 2020). "Interestingly, through Liebeskind’s research on the origin of human genes, DZIP3 originated in the eumetazoa stage, suggesting that DZIP3 may have an influence in the progression of cancer to a certain extent." (PMID 33330022, 2020). "Interestingly, DZIP3 has been shown to stabilize Cyclin D1 (CCND1) expression, which promotes cell-cycle progression and proliferation of cancer cells." (PMID 35993275, 2022).
DZIP3 also shares sentences with these, for which no sentence is quoted: colorectal cancer (1 paper).